FAS (Fas cell surface death receptor)
Diseases named in the same sentence as FAS in open-access papers (continued):
Sharing a sentence is not in itself a finding about the gene and the disease.
breast carcinoma (76 papers, 2003 to 2025). "In fact, tumor cells can escape FAS-mediated apoptosis by downregulating the FAS/FAS-L signaling pathways, which seem to be associated with poor prognosis in breast cancer patients." (PMID 38891056, 2024). "The main tumor suppressors downregulated in AT are PCDH10 (log2FC − 4.76), a protocadherin whose promoter is methylated in diffuse large B-cell lymphomas or PTPN13 (log FC: − 2.84) an inhibitor of FAS-induced apoptosis associated with aggressive breast cancer." (PMID 34183044, 2021). "There was a significant association between the FAS −670 A/G polymorphism and breast cancer risk and the −670 GG genotype is a risk factor for susceptibility to breast cancer (OR = 3.181; 95% CI = 1.21–8.33; p = 0.019)." (PMID 23326385, 2013). "Haplotype frequencies of FAS (rs2234767, rs1800682) and FasL (rs5030772, rs763110) genes polymorphisms in normal and breast cancer subjects." (PMID 23326385, 2013). "Previous researches have also addressed FAS/FASL polymorphisms in breast cancer but in some of these studies the results only partially corroborated with our findings." (PMID 23326385, 2013). "In addition, FAS carries the third-highest gene mutational frequency in pan-cancer samples, and FAS mutations have been proven to correlate with cancer development and progression in various tumor types, including malignant glioma, breast cancer, pulmonary adenocarcinomas, and cholangiocarcinoma." (PMID 35748782, 2022). "In patient-derived human breast cancer and glioblastoma neurospheres, FAS increases cancer stemness." (PMID 35249111, 2022). "FAS mRNA and protein expression levels were considerably lowered in breast carcinoma, whereas high FAS expression implies a better prognosis in breast cancer patients." (PMID 36186479, 2022). "Several studies have described the clinical outcomes related to FAS SNPs in multiple types of cancer, including lung cancer and breast cancer." (PMID 33819921, 2021). "For this reason, lots of researchers intend to activate the FAS/FASLG signaling for breast cancer treatment." (PMID 34889164, 2021). "Knockdown of STAT3 expression by siRNA induced FAS‐mediated apoptosis in vitro and in vivo in breast cancer." (PMID 34155784, 2021). "In the present study, our findings demonstrate the novel role of miR-21 in vivo for breast cancer initiation and metastases, and in sensitizing tumor cells to cytotoxic therapy by upregulating the FAS/FASL signaling pathway." (PMID 33672628, 2021). "In the present study, we demonstrate a novel role of miR-21 in vivo for breast cancer initiation and metastases, and in sensitizing tumor cells to cytotoxic therapy by upregulating the FAS/FASL signaling pathway." (PMID 33672628, 2021). "For some breast cancer cells with low FAS expression, the FAS antigen expression vector can also be transfected into cells to promote high expression before using APO-1 monoclonal antibodies." (PMID 34502549, 2021). "FAS mRNA expression can be used as a prognostic marker in certain cancers including breast cancer, gastric cancer, lung cancer, pancreatic cancer and AML." (PMID 31942177, 2020). "It was reported that FAS protein was related to a better prognosis in breast cancer, acute myeloid leukemia, urothelial cancer and lung cancer." (PMID 31942177, 2020).
breast carcinoma (continued). "The high frequency of FASL+ CTCs or Treg cells and FAS+/CD8+ cytotoxic T or CD4+ T-helper cells in patients with breast cancer indicates that CTCs hinder the anti-tumor immune response through the FAS/FASL apoptotic pathway." (PMID 32260071, 2020). "FAS mRNA expression was correlated with better OS in breast cancer, gastric cancer and lung cancer, but worse OS in pancreatic cancer and AML." (PMID 31942177, 2020). "Of note, their adverse effect on ER-positive FAS-high patient outcome indicated different functions of tumor-infiltrating CTLs with respect to breast cancer subtypes." (PMID 31016433, 2019). "In summary, FAS was identified as an independent prognostic marker for recurrence free survival in breast cancer, with large variation in expression by receptor subtypes." (PMID 28121628, 2017). "Our studies shows that besides ER-negative status, also a positive FAS-status is required for CD8+ TILs to be prognostic in breast cancer." (PMID 28121628, 2017). "The second aim is to evaluate the expression of FAS as a prognostic marker in breast cancer, both in general and in selected subtypes." (PMID 28121628, 2017). "Piperine shows apoptotic induction via downregulation of FAS gene expression in breast cancer cells." (PMID 25255125, 2014). "In fact, some immune related genes are essential in bone metastasis of breast cancer, and their family members, such as FAS, IL2RG and IL7R, have shown dysregulated in our work and have been reported to be either metastasis related or bone metastasis related." (PMID 25163697, 2014). "Resveratrol is found to suppress proliferation of cancer stem-like cells isolated from breast cancer cells through suppression of FAS expression." (PMID 25255125, 2014). "The effect of E2 in preventing FAS-activation dependent apoptosis in breast cancer cells will have an impact on therapeutic response as active Fas/FasL can amplify the pro-apoptotic effects of chemotherapeutic drugs." (PMID 23758675, 2013). "FAS rs1800682, FASL rs5030772, and FASL rs763110 genotypes showed significant associations with an increasing risk of breast cancer (odds ratio OR = 3.18, P = 0.019; OR = 5.08, P = 0.012; OR = 2.40, P = 0.024, respectively)." (PMID 23326385, 2013). "Though, FAS rs1800682, FASL rs5030772, and FASL rs763110 polymorphisms were associated with the risk of breast cancer in the examined population." (PMID 23326385, 2013). "FAS has been shown to be as effective as the AI anastrozole in postmenopausal women with advanced breast cancer resistant to TAM." (PMID 22295238, 2011). "Currently, FAS is the only FDA approved drug to treat advanced breast cancer in postmenopausal women who previously progressed on other antiestrogens." (PMID 22295238, 2011). "In the current study, we have shown that induction of TRAIL and FAS by retinoic acid in the breast cancer cell line H3396 correlates with an increase in the number of apoptotic cells." (PMID 20102612, 2010). "The ability to modulate FAS could be important, as it is induced by radiation, and the knockdown of FAS resulted in the increased survival of breast cancer cells following radiation." (PMID 33672628, 2021). "Notably, AdoMet efficiently activated caspase 8 by FAS-mediated signaling in hormone-dependent breast cancer cells while it induced apoptosis in HNSCC via the intrinsic mitochondrial pathway." (PMID 33202711, 2020). "Furthermore, combining recent evidence regarding TILs in TNBC with the earlier evidence on FAS expression, we suggest that FAS is a clinical prognostic in breast cancer as an independent alternative for TILs." (PMID 28121628, 2017).
breast carcinoma (continued). "Furthermore, we showed that FAS is an independent prognostic marker in breast cancer, independent from estrogen receptor status or other possibly confounding factors." (PMID 28121628, 2017). "We found that the FAS-1377 G/A did not affect the risk of breast cancer, while FAS −670 G/A, FASL Ivs2nt 124 A/G and FASL −844 C/T gene polymorphisms are risk factors for this disease in our study population." (PMID 23326385, 2013). "In the cancer type subgroup analysis, significant associations were detected between the FAS-1377 G/A SNP and skin carcinoma, breast cancer and ‘other cancers’, rather than gastric, lung, and prostate cancers." (PMID 24014103, 2013). "Furthermore, breast cancer cells that have acquired resistance to FAS show significant upregulation of microRNA (miRNA)-221 and -222 expression." (PMID 22295238, 2011). "For patients with advanced breast cancer, FAS is beneficial following progression on TAM therapy." (PMID 22295238, 2011). "GDF11, CD151, PAFAH1B2 and YTHDF2 may play a pivotal role in the predisposition of metastasis to the bone from breast cancer, whilst DPP9, FAS, ZNF519, RPP14 and FAU may be actively involved in the adaptative colonisation of metastatic breast cancer cells in bone." (PMID 35685372, 2022). "Moreover, they observed a significantly increased breast cancer risk associated with the FAS −1377G/A genotype, but we report lack of such association." (PMID 23326385, 2013). "In the present study we found lack of association between FAS expression and breast cancer." (PMID 23326385, 2013). "The interaction between FASLG and FAS activates RIPK1, leading to necrosome formation that trigger necroptosis in tumor cells, potentially indicating breast cancer." (PMID 38460046, 2024). "We found that AS1842856 treatment for 48 h induced FAS and/or BIM gene expression in BT549, MDA‐MB‐468 breast cancer cell lines, and DBTRG, A172 LN229, LN18, and U87MG GBM cell lines." (PMID 36602390, 2023). "At least three genes from this list were involved in the formation of carcinomas, including breast carcinoma (CASP8, HSPA4, BCL2L11), prostate carcinoma (BCL2, CASP8, BCL2L11, ATM), and chronic lymphocytic leukemia (BCL2, CASP8, FAS, BCL2L11, BAK1)." (PMID 37298337, 2023). "In other studies, β-sitosterol caused apoptosis, induced the activation of caspases in human breast cancer MDA-MB-231 cells, and also activated FAS signaling." (PMID 34679718, 2021). "Our previous study showed that 6-TG induces FAS-mediated exogenous apoptosis and p21-dependent G2/M arrest in MCF-7 breast cancer cells by regulating DNMT1." (PMID 33470407, 2021). "Our study found that the cases with high expression of FAS had a significant better OS and RFS in breast cancer." (PMID 31942177, 2020). "Therefore, tumor expression of FAS could act as a clinical prognostic marker in breast cancer." (PMID 28121628, 2017). "A number of studies have been performed evaluating the prognostic relevance of FAS and FASL in breast cancer, focusing mainly on the FASL/FAS ratio." (PMID 28121628, 2017). "We selected AXIN-1, FAS, and FGFR2 for further analysis because of their known role in breast cancer and apoptosis." (PMID 23758675, 2013). "Thus, the present study, that assesses the association between −1377 G/A and −670 A/G polymorphisms in FAS as well as single nucleotide polymorphisms −844 C/T and INV2nt −124 A/G in FASL adds an important information about the role of this death pathway in breast cancer." (PMID 23326385, 2013).
breast carcinoma (continued). "In the present study, we investigate whether the FAS-1377 G/A, FAS-670 A/G, FASL-844 T/C and FASL Ivs2nt 124 A/G polymorphism in cell death pathway genes were associated with the risk of the development of breast cancer in a sample of Iranian population (south east of Iran)." (PMID 23326385, 2013). "Here, we introduced CD74 as one of those crucial inhibitors for FAS-mediated apoptosis and our results point to the possibility that the FAS pathway is synergized and activated by the CD74-derived peptide and AKT inhibitor in breast cancer." (PMID 39056676, 2024). "Given that FAS and BIM are commonly silenced in cancer to prevent apoptosis, we examined whether these genes were also silenced in basal breast cancer cells." (PMID 36602390, 2023). "In breast cancer, HBXIP could modulate abnormal lipid metabolism and tumor growth by activating FAS signaling." (PMID 35037689, 2022). "Pathways analysis of primary breast tumors lacking miR-21 and exposed to ionizing radiation revealed apoptosis and death receptor signaling, specifically FAS/FASL signaling, to be the key signaling nodes in breast cancer treatment response in the miR-21−/− model." (PMID 33672628, 2021). "We analyzed the correlation between FAS mRNA expression and the sensitivity of different tumor cell lines to target drugs for NSCLC (vemurafenib, dabrafenib, crizotinib and carbozantinib), pancreatic cancer (erlotinib) and breast cancer (afatinib)." (PMID 31942177, 2020). "A similar mechanism may also exist in breast cancer cells, where treatment of preneoplastic MCF-10AT breast epithelial cells with anti-FAS (an activator of FAS signalling) induced c-Met/FAS complex dissociation and apoptosis." (PMID 25887320, 2015). "The results showed that the expression levels of FAS mRNA were not significantly different between breast cancer and normal tissues (P = 0.588)." (PMID 23326385, 2013). "However, none of the investigated apoptosis-related proteins (Bcl2, Bax, Bcl-xl, Bag1, FAS, FASL) could be helpful in predicting the response to drug treatment for breast cancer." (PMID 35163777, 2022). "However, the role of FAS and FASL gene polymorphisms in breast cancer has not been conclusively established." (PMID 23326385, 2013). "MCF7 and T47D breast cancer cells expressing a dominant negative IRF1 (dnIRF1), which lacks the carboxyl-terminal transcriptional activation domain, do not undergo FAS-induced cell death and are, in turn, less sensitive to AEs." (PMID 22295238, 2011).
Obesity (70 papers, 2010 to 2025). Accumulation of substantial excess body fat. "Our current study has identified the regulation of EV secretion and the expression of oncogenic proteins, specifically TMEM205, STAT5, and FAS, in obesity-associated EC tissues and serum." (PMID 39414985, 2024). "Adipose FAS mRNA expression is significantly associated with obesity, predominantly visceral fat accumulation, impaired insulin sensitivity, and circulating adipokines." (PMID 33312536, 2020). "In contrast, obesity or consumption of a high-fat diet leads to decreased levels of bilirubin and PPARα, resulting in elevated FAS (fatty acid synthase) and ACC (acetyl-CoA carboxylase) expression, which promotes triglyceride accumulation." (PMID 41425635, 2025). "At present, it is identified that the increased expression levels of adipogenic-specific genes including SREBF1, FAS, ACC and SCD1 are associated with HFD-induced obesity." (PMID 38504370, 2024). "While the oncogenic roles of STAT5, FAS, and TMEM205 have been investigated in various cancers, their involvement in the regulation of EV secretion and obesity-associated EC remains incompletely understood." (PMID 39414985, 2024). "Our study presents compelling evidence that highlights the critical role of obesity-associated EV carrying oncogenic proteins, including TMEM205, STAT5, and FAS in the pathogenesis of EC." (PMID 39414985, 2024). "Mounting evidence indicates that the administration of natural agents alleviates obesity by downregulating C/EBPα and FAS gene expression in HFD-fed mice." (PMID 36771494, 2023). "The administration of MF/MR markedly decreased the adipogenesis protein expressions of SREBP-1c, PPAR-γ, C/EBPα, and FAS in eWAT from HFD-induced obesity mice." (PMID 37686745, 2023). "Both FAS and SCD, as important factors in de novo lipogenesis, have been proven to be associated with the development of obesity." (PMID 38068770, 2023). "An elevated FAS expression level significantly increases the deposition of triglycerides in the body, leading to obesity." (PMID 36337193, 2022). "The discovery of FAS inhibitors represents an alternative strategy for the prevention of obesity, obesity-related diseases, and cancer." (PMID 34445273, 2021). "Compared with the control groups, the expression of obesity related gene IL-1β and FAS was decreased in the experimental group." (PMID 34683827, 2021). "SCD1 is involved in carbohydrate-induced activation of FAS and other lipogenic enzymes, and recently proposed as a potential therapeutic target to control obesity and the progression of related metabolic diseases including hepatic steatosis." (PMID 32772323, 2021). "For FAS, the apple polyphenol phloridzin has been reported to decrease the activity of hepatic FAS in a mouse model of obesity." (PMID 33198144, 2020). "The obesity‐induced hypotriglyceridemia and changes in hepatic PPARγ, skeletal muscle FAS, and white adipose tissue FATP1 and FAS are similar to that observed for pregnant rodents fed an obesogenic diet during pregnancy alone." (PMID 31466137, 2019). "In accord with its anti‐obesity effect in older mice, an aging‐related increase in mRNA level of FAS in 16‐month‐old WT mice was observed, which was inhibited by endothelium‐specific CYP2J2 overexpression." (PMID 29318723, 2018). "Previous reports have shown that FAS can be a potential drug target because its inhibition can reduce food intake and obesity in mice." (PMID 29695233, 2018). "Jatrorrhizine can also down regulate the expressions of SREBP-1c and FAS in the liver of high-fat diet-induced obesity mouse model." (PMID 29930696, 2018). "Renal FAS mRNA expression was increased by two fold by maternal obesity (HC vs. CC p < 0.01), suggestive of upregulated fatty acid production." (PMID 27004609, 2016). "It is possible that FAS and FADD work together to play a critical role in obesity and obesity‐associated pathologies." (PMID 27357657, 2016).